INS (insulin)
Diseases named in the same sentence as INS in open-access papers (continued):
Sharing a sentence is not in itself a finding about the gene and the disease.
Hypoglycemia (continued). "Compared with conventional insulin pump therapy, dual-hormone closed-loop systems have been shown to reduce hypoglycemia, improve mean glucose levels, and increase time spent in the target glycemic range." (PMID 35733769, 2022). "Thirty-one cats were evaluated for the time to development of hypoglycemia following insulin and dextrose administration, and eight (26%) developed hypoglycemia within 12 h." (PMID 36350735, 2022). "Glucose concentrations were generally in the normal range in the time preceding intravenous insulin administration, but there was a drop to hypoglycemia in the 15–30 min after." (PMID 36351679, 2022). "Glycemic control: A variability coefficient assessed by continuous glucose monitoring (Free Style® sensor), mean insulin dose and hypoglycemia rates obtained with the two treatments were analyzed." (PMID 35628938, 2022). "Metformin can be combined with insulin to increase the hypoglycemic effect of insulin, reduce the amount of insulin, and prevent hypoglycemia." (PMID 35401934, 2022). "Under HA/HR conditions, metabolism is higher and there is an increased dilation of blood vessels; both factors lead to increased absorption of insulin, which induces hypoglycemia." (PMID 35497950, 2022). "The BG-normalizing property of HM15136 was assessed in an insulin-induced acute hypoglycemia rat model." (PMID 36202918, 2022). "The adjusted OR for neonatal hypoglycaemia was 0.4, 0.3 and 0.3 for 1st, 2nd and 3rd trimester exposure, respectively (p = 0.07; p = 0.03; p = 0.05, respectively), after adjustment for insulin use, gestational age and LGA." (PMID 34427780, 2022). "Hypoglycaemia has been reported to occur up to six hours following insulin treatment and therefore frequent monitoring of the serum glucose concentration is needed to detect this serious complication and prevent it from causing neurological damage." (PMID 35552566, 2022). "Common positive themes included: improved glucose management, improved nighttime control, favoring automated insulin delivery, hypoglycemia prevention, and reduced cognitive burden." (PMID 35853530, 2022). "When intensive PA is added, the process is more demanding, requiring frequent testing, insulin adjustment, and tighter control of glycemia that can build a sense of hypervigilance against hypoglycemia." (PMID 36420398, 2022). "The patient presented with recurrent episodes of hypoglycemia, and the doses of preprandial and basal insulin were reduced." (PMID 35918735, 2022). "Our study design was limited to addressing the effects of portal insulin, glucose concentration, or hypoglycemia on insulin clearance." (PMID 35887007, 2022). "Hypoglycemia is the most common and feared adverse effect of insulin therapy and is the most significant barrier to the maintenance of near-normoglycaemia." (PMID 35571045, 2022). "GH is a counter-regulatory hormone of the action of insulin and therefore, changes in glucose metabolism have been associated with GHD, such as hypoglycemia, especially in children." (PMID 36557289, 2022). "Although hypoglycaemia is a frequent complication of insulin therapy, it is often under-appreciated." (PMID 35552566, 2022). "Poor kidney function increases the half-life of insulin, resulting in hypoglycaemia which typically occurs 1–3 hours after insulin administration." (PMID 35552566, 2022). "This, in turn, affects glycemic control, resulting in unexplained hypoglycemia and a significant increase in blood glucose change levels, which leads to an increase in insulin costs." (PMID 35574009, 2022). "Participants with HbA1c below 53 mmol/mol (7%) spent 2.34% (IQR: 0.60–4.49) and 5.61% (0.34–13.80) of their total time per week in hypoglycemia (<3 mmol/L), for SU and insulin, respectively." (PMID 35450869, 2022). "In hypoglycemia, cortisol, adrenaline, and noradrenaline protect cells by inhibiting insulin activity, inducing protein catabolism, and enhancing gluconeogenesis and glycogenolysis." (PMID 36248663, 2022).
Hypoglycemia (continued). "One common acute complication is hypoglycemia, a state of low blood glucose (BG) concentration that results from excessive insulin administration." (PMID 35394448, 2022). "While normally functioning beta cells make and release insulin, pancreatic alpha cells are responsible for the production of the hormone glucagon, the release of which occurs in response to hypoglycemia and is suppressed by elevations in blood glucose." (PMID 36992764, 2022). "All 25 dogs were also hypoglycaemic; 23/25 dogs had an inappropriate fasting insulin level in the presence of hypoglycaemia." (PMID 35079406, 2022). "At the same time, a formal fasting study showed fasting tolerance of 13 h before hypoglycemia occurred (plasma glucose 48 mg/dL [2.66 mmol/L], insulin 4.6 mU/L, BHB 0.1 mmol/L, FFA 0.49 mmol/L)." (PMID 35897673, 2022). "Congenital hyperinsulinism (CHI) is a disorder characterised by severe hypoglycaemia due to inappropriate secretion of insulin by the pancreatic β-cells." (PMID 35928891, 2022). "An adverse effect of insulin therapy was hypoglycemia, which is already in itself a factor of a worse neurological outcome." (PMID 36291477, 2022). "Taking into account the discordant values of insulin and C-peptide it was decided to perform a fasting test to re-examine these hormones during hypoglycemia." (PMID 36376919, 2022). "Because dapagliflozin reduced total insulin dosage, hypoglycemia due to high insulin dosage was impossible to occur theoretically." (PMID 35872994, 2022). "Insulin administration induced hypoglycemia, with a mean lowest blood glucose value of 34.2 ± 8.6 mg/dL (range 20–50 mg/dL)." (PMID 35173220, 2022). "Until recently, glucagon was considered a mere antagonist to insulin, protecting the body from hypoglycemia." (PMID 36686477, 2022). "The aim of this real-world prospective study is to assess the impact of hypoglycemia on productivity and utility in insulin-treated adults with T2DM from Ontario and Quebec, Canada." (PMID 35343912, 2022). "It included lowering insulin doses in alignment with caloric restrictions to prevent hypoglycaemia or treating those with leptin resistance with medications to boost anorexigenic effects while they worked towards developing self-maintenance strategies." (PMID 36232191, 2022). "Both groups acknowledged the importance of glycemic control and the need to report details of blood glucose, hypoglycemia, and insulin regime." (PMID 36378513, 2022). "It has been shown that GIP stimulates insulin release to exert hypoglycemic effects under hyperglycemic conditions, while stimulating glucagon secretion to reduce the occurrence of hypoglycemia in hypoglycemic states." (PMID 36119737, 2022). "For example, reducing insulin basal and/or bolus doses prior to exercise can prevent hypoglycaemia during aerobic exercise, however aggressive reductions can cause hyperglycaemia." (PMID 36246914, 2022). "The main reasons for the occurrence of hypoglycemia are the failure to adjust the insulin dose to food intake or physical activity." (PMID 35620854, 2022). "We have chosen egg whites as an immune challenge and insulin-induced hypoglycaemia as a metabolic stressor." (PMID 35163282, 2022). "When confronted with evidence about factitious hypoglycaemia, all patients admitted the intentional insulin injecting or glibenclamide ingestion." (PMID 36117266, 2022). "Main outcomes were HbA1c, body weight, insulin dose changes, hypoglycemia, and other adverse events." (PMID 35573995, 2022). "Differential diagnoses of canine insulinoma can be excluded by simultaneously measuring their insulin levels at the time when the hypoglycaemia is diagnosed." (PMID 36288153, 2022). "Another patient had only ‘traces’ of urinary ketones detectable after hypoglycemia, so an insulin-mediated mechanism seems possible." (PMID 35897673, 2022).
Hypoglycemia (continued). "The novelty of this study was the demonstration that miRNAs are both up-regulated and down-regulated at hypoglycemia, an insult that occurred within 1-hour of initiating the insulin infusion, and that these changes were only seen in controls and not in T2D." (PMID 36017315, 2022). "The proportion of insulin use in patients in hypoglycemia group (n=1575, 56.2%) was much higher than that for patients in the normoglycemia group (n=7306, 27.0%)." (PMID 35708754, 2022). "Long-acting insulin analogues SHOULD BE CONSIDERED for basal insulin therapy, as they induce less glycemic variability and lower incidence of nocturnal hypoglycemia compared to NPH insulin." (PMID 36510287, 2022). "Hetherington and Ranson have demonstrated that lesion of the VMH results into a massive obesity and marked adiposity in rats, and another study revealed that VMH lesions blunt CRR to insulin-induced hypoglycemia." (PMID 35619170, 2022). "It would be necessary to extend the diagnosis of CAI by performing the metyrapone test or the insulin-induced hypoglycemia test." (PMID 36465638, 2022). "Four participants needed clinical support to adjust their insulin dose due to recurrent hypoglycemia, which was discussed with an endocrinologist from the multidisciplinary team." (PMID 35595850, 2022). "SMBG is especially important for insulin-treated patients to monitor for and prevent hypoglycemia and hyperglycemia." (PMID 35222287, 2022). "This is in line with the reported sympathetic response to insulin-induced hypoglycemia by increasing glucagon secretion." (PMID 36327900, 2022). "This improved glucose tolerance was not accompanied with an enhanced insulin sensitivity, as all the groups suffered from a similar degree of hypoglycemia upon an exogenous administration of insulin." (PMID 36362376, 2022). "A study induced stress by several stressors, such as chronic subcutaneous administration of corticosterone and insulin-induced hypoglycemia in rats, and found that the former decreased kisspeptin expression in the mPOA and ARC; however, the latter did not." (PMID 36359090, 2022). "Of the remaining 5/30 dogs, four were diagnosed based on an inappropriate fasting insulin level in the presence of hypoglycaemia, combined with an imaging findings of a pancreatic nodule on CT (n = 2) or ultrasound (n = 2), with no pathological confirmation." (PMID 35079406, 2022). "A descriptive analysis of data on glycemic control parameters, insulin treatment regimen, frequency of hypoglycemia and severe hypoglycemia." (PMID 35758838, 2022). "The LOGIC-Insulin software advises the nurse on the insulin dosage (or a dextrose bolus in case of hypoglycemia) as well as on the next blood sampling interval." (PMID 36123593, 2022). "Insulin secretion and hypoglycemia were reduced and survival prolonged in mice with functional PanNETs, and metastatic tumor burden was decreased to less than the onset of treatment in mice with metastatic PanNETs." (PMID 35118189, 2022). "As a result, inherent liabilities (e.g. hypoglycemia) of injectable insulin continue to limit the true therapeutic potential of related agents." (PMID 35177603, 2022). "Although the MBG of both groups were similar, the basal insulin group had lower GV, overall hypoglycaemia and nocturnal hypoglycaemia than the premixed insulin group." (PMID 35574003, 2022). "The median age at diagnosis at HI of the 10 individuals was 101 days (IQR 1–581 days) with insulin detected at the time of hypoglycaemia (plasma glucose <2.8 mmol/L) in all cases." (PMID 35294086, 2022). "The median time to hypoglycemia for all eight cats that developed hypoglycemia after receiving insulin during only the first hour of treatment was 5.5 h (range 2–11)." (PMID 36350735, 2022). "Insulinoma is an uncommon insulin-secreting neuroendocrine tumor that presents with severe recurrent hypoglycemia." (PMID 36494838, 2022).
Hypoglycemia (continued). "Five participants (17%) routinely consumed bedtime snacks to avoid exercise-related overnight hypoglycaemia; however, four of those participants also routinely administered an insulin bolus dose with these snacks." (PMID 35233639, 2022). "The children that participated in the study had appropriate suppression of insulin secretion in response to hypoglycemia and had a normal fasting tolerance, arguing against an underlying disorder of insulin secretion." (PMID 35399928, 2022). "Of these eight cats that developed hypoglycemia after only a single dose of insulin, six (19%) became hypoglycemic within 6 h, with a median time to hypoglycemia of 5 h (range 2–6)." (PMID 36350735, 2022). "Prandial hyperinsulinemia several years after GB, particularly in those with GB-related hypoglycemia, has been attributed to both exaggerated β-cell output and possibly reduced insulin clearance." (PMID 35887007, 2022). "Combining plasma glucose, insulin and C-peptide, insulinoma patients have higher fasting insulin and fasting C-peptide than the control group, indicating that insulinoma patients are more likely to have fasting hypoglycemia symptoms." (PMID 35916979, 2022). "Glucagon’s ability to increase blood glucose concentrations seems to be influenced by the concentration of circulating insulin, and it is most effective in situations with impending hypoglycaemia and low systemic insulin concentrations." (PMID 36213069, 2022). "The net effect of the breakdown of this intra-islet homeostasis results in the dysregulation of insulin secretion, leading to significant hypoglycemia." (PMID 36237195, 2022). "Initially, the pharmacokinetics of insulin preparations had been determined indirectly based on the degree and duration of the hypoglycemia impact following injection." (PMID 35723344, 2022). "Although it is extremely rare, antibodies against both endogenous and exogenous insulin are capable to induce intractable hypoglycaemia via binding with insulin and disrupting its normal function." (PMID 36440205, 2022). "To establish a model of hypoglycemia-associated autonomic failure (HAAF), we used a previously reported insulin injection protocol." (PMID 36676967, 2022). "Hypoglycemia is a relatively common complication in diabetic patients, particularly those on insulin therapy." (PMID 35858952, 2022). "This is accomplished by interrupting insulin delivery when glucose values reach or drop below a specified threshold [Low-Glucose Suspend (LGS) system] or even before hypoglycemia is reached (predictive LGS)." (PMID 36275049, 2022). "The side effects of insulin therapy range from mild to severe, including hypoglycemia, weight gain, insulin allergic reaction, and lipoatrophy or lipohypertrophy at the site of injection." (PMID 36654645, 2022). "After discussing the results with the patient, we told her that continuation of surreptitious insulin injections to induce hypoglycemia puts her life and health in danger." (PMID 36376919, 2022). "In the unadjusted multinominal logistic regression model, the RRR for hypoglycaemia was 7.90 (95% Cl 2.92–21.38) with bolus-only insulin, 65.87 (95% Cl 26.05–166.57) with basal-bolus insulin, and 42.83 (95% Cl 14.83–112.21) with premixed insulin." (PMID 34986826, 2022). "We developed the predictive score comprising age > 60 years old, pretreatment blood glucose ≤ 100 mg/dL (≤ 5.6 mmol/L), and pretreatment potassium > 6 mmol/L to predict posttreatment hypoglycemia complicating from insulin treatment in the hyperkalemic patient." (PMID 36371171, 2022). "Hyperinsulinism (HI) is a disorder of the pancreatic beta‐cell where inappropriately high levels of insulin are secreted leading to hypoglycaemia." (PMID 35294086, 2022). "All of the patients were managed according to the modified DKA protocol, with a requirement of change of fluid in 34.2% (n = 65) and a decrement of insulin by half due to recurrent hypoglycaemia in 3.2% (n = 6)." (PMID 36102127, 2022).
Hypoglycemia (continued). "Additionally, insulin therapy for a long time is unsatisfactorily associated with some disadvantages, such as insulin resistance, weight gain, dyslipidemia, and hypoglycemia, that are of deep concern in T1DM because they could influence therapy compliance and result in an increased mortality rate." (PMID 35872994, 2022). "Some authors suggest paying particular attention to the fact that death from hypoglycemia can occur even after a prolonged comatose state, a period that can allow the elimination of insulin, its metabolites, and other substances." (PMID 36359343, 2022). "Hypoglycemia is an unfortunate side-effect of intensive insulin therapy and can occur when an inappropriately large dose of insulin is injected." (PMID 36676967, 2022). "Both studies revealed significant reductions in HbA1c, insulin doses, and body weight, but higher rates of hypoglycemia and ketosis (ketone level >1.5 mmol/L), especially in the higher-dosed groups." (PMID 35745754, 2022). "Reductions in insulin basal and/or bolus dose can be used in addition to, or alongside, carbohydrate intake for the prevention of exercise-induced hypoglycaemia." (PMID 36246914, 2022). "Some studies recommend that lower CV targets (<33%) enhance protection against hypoglycemia for patients on insulin therapy." (PMID 36011925, 2022). "This remained after further adjustment for other variables, including severe hypoglycemia within the previous 3 years; insulin, sulfonylurea, and glinide use; and history of hypertension, CKD, and CVD (model 3)." (PMID 35195697, 2022). "Almost half of the participants (n=11; 44%) reported applying one, or a combination of insulin- and CHO-based strategies to reduce the risk of nocturnal hypoglycemia the night following ACT." (PMID 36237197, 2022). "Under normal physiological conditions, secretion of insulin from the β cell is precisely regulated to prevent hypoglycemia or hyperglycemia." (PMID 35296370, 2022). "This review shows that sodium lactate can be safely administrated to humans with insulin-induced hypoglycemia, TBI, Alzheimer’s disease, or heart failure." (PMID 35304646, 2022). "Inappropriate insulin secretion by the β-cells of the pancreas results in hypoglycemia, neuronal energy deprivation, and parieto-occipital brain injury." (PMID 35721755, 2022). "Information regarding dietary intakes (quantity and quality) and insulin adjustments as mitigation preventive strategies, as well as nocturnal hypoglycemia or nocturnal hypoglycemia correction, was sometimes incomplete or not reported." (PMID 36237197, 2022). "The data analysis from the DPV database included approximately 16,460 insulin pump users and reported lower rates of hypoglycemia and diabetic ketoacidosis episodes, compared with injections users (9.55 vs. 13.97 and 3.64 vs. 4.26 per 100 patient-years)." (PMID 36422210, 2022). "This barrier represents a complex set of beliefs (eg, sense of failure and incompetency) and attitudes (eg, fear of injections and hypoglycemia) toward insulin therapy." (PMID 35943787, 2022). ">150 mg/dl should trigger insulin therapyTreatment goal: <150 mg/dl in ICU.Maintain glucose levels <180 mg/dl while avoiding hypoglycemia." (PMID 35831938, 2022). "Incretins contribute to the post-prandial hypoglycemia via increased GLP-1 release potentiating insulin secretion." (PMID 35399928, 2022). "Our results showed that chronic injection of GnIH significantly weakened insulin-induced hypoglycemia between 30 and 75 min after insulin challenge (p < 0.05)." (PMID 35897643, 2022). "For instance, hypoglycaemia, triggered by an insulin infusion, increases β-endorphin levels and during exercise, when glucose is needed to fuel muscle activity, β-endorphin secretion into the blood is enhanced." (PMID 35593927, 2022). "Monotherapy using acarbose does not cause hypoglycemia, but the use of other antidiabetic drugs, such as sulfonylurea or insulin, induces hypoglycemia." (PMID 36552346, 2022).